SOD3 (superoxide dismutase 3)
Diseases named in the same sentence as SOD3 in open-access papers (continued):
Sharing a sentence is not in itself a finding about the gene and the disease.
cancer (continued). "Although SOD3 is generally downregulated and considered a tumor suppressor gene in most cancers, its role appears to be dual and context-dependent." (PMID 41028519, 2025). "Mechanistically, transcriptome analysis revealed that SOD3 overexpression in CAF enhanced cancer exacerbation-related genes, particularly angiogenesis, lymph vessel development, collagen degradation, and epithelial-mesenchymal transition." (PMID 41028519, 2025). "Overexpression of SOD1 and SOD3 in cancers helps to maintain cellular ROS under the critical threshold, and improve response to chemotherapy, respectively." (PMID 40426890, 2025). "Recently, decreased expression of SOD3 has been observed in several types of cancer, including lung cancer, as well as in highly invasive tumor cells compared to those with low invasiveness." (PMID 39589950, 2024). "SOD3 is differentially expressed in cancer and this research utilises Gene Expression Omnibus data series GSE2109 with 2,158 cancer samples." (PMID 39480826, 2024). "Conversely, Laukkanen has shown that enhancing SOD3 activity or expression through endogenous administration of recombinant SOD3 or induction of SOD3 expression can inhibit cancer cell metastasis." (PMID 39430913, 2024). "The remaining one gene, SOD3 was downregulated in Xenopus tumor whereas it was upregulated in human cancer." (PMID 37580380, 2023). "Studies of SOD1, SOD2, or SOD3 in colorectal, lung, and other cancers have also been widely reported." (PMID 37759978, 2023). "Analyzing how SOD3 re-expression affects the interaction of stromal and cancer cells in the TME is, therefore, of great interest." (PMID 35267534, 2022). "Therefore, high SOD3 levels in the tumor vasculature shifted the laminin α4/α5 balance towards the laminin-α4high/laminin-α5low phenotype, which is permissive for T cell diapedesis into tumors and explains the improved cancer immune surveillance associated to high SOD3 levels." (PMID 35267534, 2022). "In tumors induced by control (EG7-mock) and SOD3-overexpressing (EG7-SOD3) cancer cells, laminin α5 staining only appeared in close proximity to the endothelial cell marker CD31+, suggesting localization in the endothelial BM." (PMID 35267534, 2022). "The previous study reported that the maintenance of high SOD3 expression in cancer cells is important for suppressing cancer progression." (PMID 35457131, 2022). "According to the box diagram, the expression level of SOD3 was similar between the central cancer cells and the peripheral cancer cells." (PMID 35356201, 2022). "This controversial role of SOD3 is in line with other studies showing the dual function of SOD3 in regulating cancer progression." (PMID 36077709, 2022). "Clinical researchers can detect the SOD3 gene in cancer patients, and consider using chemotherapy drugs for patients with low SOD3 expression." (PMID 35356201, 2022). "On the other hand, SOD3 highly expressed mesenchymal stem cells showed an immunomodulatory function and potential therapeutic effects in diseases including cancers." (PMID 36359248, 2022). "The data additionally demonstrated the activation of a large network of cancer-related signaling molecules by sod3 overexpression, corroborating the previous reports suggesting the growth regulatory nature of the enzyme." (PMID 33919252, 2021). "SOD3 has been shown to activate signaling pathways in tissue injuries, inflammation, and cancer models." (PMID 33919252, 2021). "Our current data suggested a correlation between the inhibition of cell migration and reduced SOD3-driven phosphorylation of EphA2, which promoted cancer cell migration, but the exact mechanism explaining SOD3 function in cell migration remains elusive." (PMID 33919252, 2021). "The Matrigel migration assay demonstrated a significant (p < 0.001) downregulation of cancer cell locomotion by SOD3." (PMID 33919252, 2021).
cancer (continued). "SOD3 protects the integrity of HS by reducing heparanase expression and by preventing ROS-mediated HS degradation, thus reducing cancer cell proliferation and invasion." (PMID 33250894, 2020). "In cancer, SOD3 upregulation increases mean vessel area and tumor vessel length, although reduces vessel diameter." (PMID 33250894, 2020). "In papillary thyroid cancer (PTC), the regulation of SOD3 found to modulate cancer cell growth and migration." (PMID 32128111, 2020). "It is also reported that increased SOD3 mRNA expression resulted in apoptosis and death of cancer cells and suggestive of cell viability." (PMID 32650602, 2020). "The chromosomal region containing the SOD3 gene (4p15.1–4p15.3) is a hotspot for loss of heterozygosity (LOH) in cancer; an LOH rate of 30–60% is seen in tumors with low SOD3 levels." (PMID 33250894, 2020). "In conclusion, cancer cells are subjected to suppress autocrine production of SOD3 and conversely trigger MSCs to secrete SOD3 demonstrating paracrine effect through modulation of cell growth, chemotactic cytokine expression and cancer cell migration." (PMID 32128111, 2020). "Several antioxidant proteins are up-regulated in chemoresistance such as SOD1, SOD2, and SOD3 in oxaliplatin-resistant cancer cells or SOD1 and Prx1 in 5-FU chemoresistance." (PMID 31658599, 2019). "Although SOD3 expression at physiological levels supports growth, the enzyme is paradoxically downregulated in certain cancers." (PMID 29478325, 2019). "Various works using transgenic SOD3 mice or adenovirus gene transfer techniques have demonstrated the inhibitory function of SOD3 on cancer cell proliferation and tumor growth." (PMID 29478325, 2019). "SOD3 expression is frequently diminished in breast and other types of cancer, which contributes to metastasis." (PMID 30941174, 2019). "Similar to SOD2, early studies have suggested that SOD3 is a tumor suppressor gene downregulated in cancer." (PMID 29478325, 2019). "In view of the results showed in this work, we propose SOD3 as a novel target for therapy in angiogenesis-dependent diseases such as cancer." (PMID 29707113, 2018). "Taken together, our results support a pro-angiogenic role for SOD3 and identify it as a promising target for anti-angiogenic therapy in cancer and other angiogenesis-related diseases." (PMID 29707113, 2018). "To probe the paracrine effect of SOD3 expression on cancer cell growth, we over-expressed SOD3 in Thyroid MSCs (Thyroid MSC SOD3) and silenced the gene expression by SOD3 RNAi in PTC MSCs (PTC MSC SOD3 RNAi)." (PMID 28216675, 2017). "To confirm the increased SOD3 levels in the PTC MSCs, we analyzed the mRNA expression of the enzyme from each patient and determined the stimulatory effect of TPC1 cancer cell condensed medium on SOD3 mRNA levels." (PMID 28216675, 2017). "We have previously shown that RAS-BRAF-MEK1/2-ERK1/2, a major signal transduction pathway in cancer, activates SOD3 mRNA expression and enzyme activity in vitro and in vivo, which then increases GTP loading to RAS." (PMID 27293512, 2016). "In aggressive anaplastic cancer cells, moderate sustained overexpression of SOD3 stimulates tumorigenesis and growth factor signal transduction." (PMID 26550576, 2015). "The inhibition of HDAC function by TSA treatment had only a minor effect on sod3 expression in cancer cells or FRLT5 cells harboring high RAS activity." (PMID 26550576, 2015). "To evaluate the effect of SOD3 over-expression on biological processes we studied the effect of SOD3 on the aggressiveness of these cancer cells." (PMID 25751262, 2015). "SOD1 stayed at similar levels, SOD2 expression increased in cancer, and SOD3 mRNA synthesis decreased correlating to reduced differentiation degree of thyroid tissue." (PMID 26664298, 2015). "The second class involves permanent silencing of SOD3 mediated by epigenetic DNA methylation in cells that represent more advanced cancers." (PMID 26550576, 2015).
cancer (continued). "The results thus suggest that methylation-mediated SOD3 downregulation in cancer corresponds to the degree of differentiation of the cancer and to the activation level of the RAS small GTPase." (PMID 26550576, 2015). "However, studies have demonstrated that SOD3 can either promote or inhibit cell proliferation and survival in various cancers, and its molecular mechanisms within the tumor microenvironment are poorly understood." (PMID 41028519, 2025). "This paradox reflects the context-specific influence of SOD3, which may vary depending on cancer subtype, cellular compartment (tumor cells vs. stromal cells), and broader microenvironmental factors." (PMID 41028519, 2025). "These facts indicate that the relationship between SOD3 and cancer remains controversial." (PMID 41028519, 2025). "Additionally, superoxide dismutase 3 (SOD3)’s role in cancer is multifaceted, acting as both a tumor suppressor and a modulator of the tumor microenvironment." (PMID 40558258, 2025). "Taken together, targeting cell-specific SOD3 may represent a promising treatment strategy for cancer." (PMID 41028519, 2025). "Interestingly, this stromal SOD3 promoted cancer cell proliferation but suppressed migration in co-culture experiments, suggesting a differential impact compared to tumor cell-intrinsic SOD3." (PMID 41028519, 2025). "Copper chelation therapy may aid SOD3 in removing O2- and be of therapeutic benefit to cancer patients." (PMID 39480826, 2024). "Moreover, Dyrk1B up-regulates the expression of several antioxidant genes, e.g., superoxide dismutases 2 and 3 (SOD2, SOD3) and ferroxidase in cancer cell lines." (PMID 38675189, 2024). "Thus, it can be considered that SOD1, SOD2, or SOD3 play an important role in colorectal cancer, lung adenocarcinoma, and other cancers." (PMID 37759978, 2023). "The expression of SOD3 in the dermis may be related to the protection of matrix components against superoxide, which may be effective in preventing skin ageing and cancer." (PMID 36982774, 2023). "In many tumors, SOD3 is downregulated and promotes cancer metastasis and malignant progression." (PMID 38201509, 2023). "The reduced expression of SOD3 may be due to the increased activity of miR-328 in G1 cancer and miR-363 in G3 cancer." (PMID 36555458, 2022). "Hence, the enhanced expression of SOD3 resulting from knocking out AK3 is interesting as a potential factor in suppressing cancer." (PMID 35457131, 2022). "More and more new cancer research focuses on the function of SOD3." (PMID 35356201, 2022). "In cancer, a recent study has shown a relationship between vascular normalization and changes in the expression of laminin α4-containing isoforms in the BM of tumor blood vessels, driven by high levels of the superoxide dismutase-3 (SOD3) in the TME." (PMID 35267534, 2022). "Various studies also confer the possible role of SOD3 in modulating the ECM dynamics in cancer." (PMID 32128111, 2020). "Depending on the microenvironment and the model system, the role of SOD3 in cancer progression remains unclear and has been shown to regulate both cell proliferation and survival." (PMID 32128111, 2020). "However, SOD3 gene silenced PTC MSCs demonstrated decreased TPC1 cell growth compared to parenteral PTC MSCs suggesting PTC MSCs support cancer cell growth through secretion of SOD3." (PMID 32128111, 2020). "A number of reports have demonstrated that SOD3 has antioxidative, antiapoptotic, anti-inflammatory, and growth-promoting characteristics in tissue injury models, in genetically modified mice, and in cancer models." (PMID 29478325, 2019). "SOD3 silencing thus appears to be common in several malignant tumors." (PMID 29422508, 2018). "Paracrine secretion of SOD3 then continues to support cancer cell growth and, correspondingly, decreases the affinity of cancer cells to tumor stroma by decreasing chemotactic cytokine expression, allowing local intratumoral cancer cell migration." (PMID 28216675, 2017).
cancer (continued). "However, in cancer SOD3 has been shown to either increase or decrease cell proliferation and survival depending on the model system used, indicating that SOD3-derived growth mechanisms are not completely understood." (PMID 27293512, 2016). "Robust supraphysiological expression of SOD3, which has been shown to reduce primary tumor growth metastasis and cancer cell proliferation, reduces the expression of GEFs and increases the expression of GAPs and GDIs, resulting in inhibition of the activation of downstream ERK1/2 kinases." (PMID 27293512, 2016). "Treatment with TSA significantly (p < 0.001) decreased sod3 mRNA expression in all of the thyroid cells that model normal thyroid, while only a tendency towards increased expression was observed in transformed and cancer cells." (PMID 26550576, 2015). "To determine whether VEGF-C regulates SOD3 in human cancers, we examined whether their expression correlates in tumors." (PMID 25358638, 2014). "Furthermore, sc RNA sequence analysis revealed that in advanced-stage tumor groups, functional analysis of SOD3-expressing fibroblasts observed the enrichment in gene sets associated with the EMT process, collagen degradation, and multi-cancer invasiveness signature." (PMID 41028519, 2025). "However, it has been indicated that stromal secreted SOD3 could stimulate cancer cell growth and inhibit cancer cell migration, and high stromal score was significantly associated with improved PFS in patients with PTC." (PMID 36950012, 2023). "SOD3 may thus increase the infiltration of anti-tumor effector cells into the TME, explaining the better prognosis associated with high SOD3 levels in some types of cancer." (PMID 35267534, 2022). "However, the authors speculated that an autocrine–paracrine conversion of SOD3 expression from cancer cells to the stromal compartment may justify the controversial role of SOD3 in cancer." (PMID 36077709, 2022). "SOD3 might therefore act as a cancer cell-intrinsic and extrinsic tumor suppressor." (PMID 33250894, 2020). "In addition, MSCs-secreted SOD3 found to modulate cancer cell migration." (PMID 32128111, 2020). "Therefore, the data may suggest that, at the late phase of carcinogenesis, the autocrine/paracrine switch maintains SOD3-driven growth support but, at the same time, releases epithelial cancer cells to migrate toward normal healthy tissue." (PMID 29478325, 2019). "Therefore, a SOD3 mimetic, like PNA, may be suitable as a targeted therapy to replace the deficient SOD3 in cancer cells." (PMID 30941174, 2019). "At the tissue level, supraphysiological SOD3 overexpression correlates with reduced oxidative stress marker 4-hydroxynonenal staining in xenografted tumors and decreased intracellular dihydroethidium staining in cancer cells transduced with adenovirus expressing SOD3." (PMID 27293512, 2016). "Interestingly, SOD3 expression is mildly upregulated in benign tumor model systems whereas it is downregulated in several cancers and in transformed cell lines suggesting that the enzyme might be involved in the initiation of benign hyperplasia." (PMID 25751262, 2015). "To further investigate the influence of SOD3-rich CAFs on tumor development, we established tumor models implanting LUAD cancer cells (PC9) together with either the CAF or the CAFSOD3." (PMID 41028519, 2025). "Protein-level analyses in nine cancer types revealed decreased expression of PLCB4, SOD3, and THRA, alongside increased expression of HMGB2 and RAC2, relative to normal tissues." (PMID 40852729, 2025). "Therefore, SOD3 could act as an intrinsic and extrinsic tumor suppressor of cancer cells." (PMID 39589950, 2024).
cancer (continued). "The dysfunction of copper-containing secretory enzymes, including superoxide dismutase 3 (SOD3) and lysyl oxidase (LOX), profoundly impacts cancer metastasis by promoting angiogenesis, epithelial–mesenchymal transition, and cancer cell invasion." (PMID 39430913, 2024). "At the same time, SOD3 overexpression decreases dimethylbenzanthracene/TPA-induced tumor formation and suppresses cancer cells’ growth in vitro and in vivo." (PMID 36552527, 2022). "The qRT-PCR results from 10 paired LUAD samples showed that the expression of SOD3 and SLC31A2 in cancer tissues was significantly lower than that in normal lung tissues, whereas LOXL2 has highly expression in LUAD tissues (P < 0.05)." (PMID 36524120, 2022). "However, in many cancers, SOD3 has been shown to increase or decrease cell proliferation and survival, but the specific conclusions remain unclear, indicating that the mechanisms of SOD3 derived growth are not fully understood." (PMID 35356201, 2022). "Our findings demonstrate that the SOD3-mimetic activity of an extracellular albumin-based macromolecular nitroxide, PNA, converts cancer cells from a tumorigenic state to a cytostatic state by reducing superoxide and ROS levels." (PMID 30941174, 2019). "Indeed, SOD3 was first identified as a therapeutic enzyme being able to inhibit efficiently liver damage in a paracetamol intoxication model, cardiovascular damage in a reperfusion model, and neointima growth in a restenosis model and only recently shown to promote unwanted growth in cancer models." (PMID 29478325, 2019). "In advanced cancers, RAS-induced epigenetic methylation and acetylation have been shown to contribute to more pronounce silencing of SOD3." (PMID 29478325, 2019). "The comparison of the average SOD1, SOD2, and SOD3 mRNA synthesis in normal and PTC showed 4.6% (SD 4.9), 3.5% (SD 17.1), and 18.6% (SD 13.1) decreased expression in cancer, respectively." (PMID 29478325, 2019). "The SOD3 mimetic activity of PNA can break down ROS, such as superoxide, and alter the ROS balance within cancer cells and the tumor microenvironment." (PMID 30941174, 2019). "The design of PNA, consisting of a novel combination of a HSA and nitroxide as a metal-free superoxide dismutase (SOD3) mimetic, has advantages over small molecular weight and membrane permeable nitroxide that mimics SOD1, SOD2, and SOD3, in cancer therapy." (PMID 30941174, 2019). "The analysis of the effect of SOD3 on TPC1 cell migration showing significantly (p < 0.01) reduced migration toward SOD3 over-expressing Thyroid MSCs (Thyroid MSC SOD3) could suggest regulation of local cancer cell migration by paracrine secretion of the enzyme." (PMID 28216675, 2017). "Disulfiram (DSF), currently in clinical cancer trials is activated by copper chelation, being potentially capable of diminishing the copper dependent activation of MEK1/2 and SOD1/SOD3 and promoting reactive oxygen species (ROS) toxicity." (PMID 26356671, 2015). "We demonstrate that a low level of RAS activation increases SOD3 mRNA synthesis that then gradually decreases with increasing levels of RAS activation and the decreasing degree of differentiation of the cancer cells." (PMID 26550576, 2015). "Once SOD3 expression levels reach non-physiological toxic levels, cancer cells decrease the autocrine SOD3 generation." (PMID 36077709, 2022). "The expression of SOD3 decreases as cancer progresses, and the non-involvement of SOD3 is considered to enhance the growth of cancer." (PMID 35457131, 2022). "In the case of SOD3 and AQP1, their expression was significantly altered in G2 and G3 cancer." (PMID 36555458, 2022). "The results were contrary to previous finding, which showed that 25 μM daidzein enhanced the expression of antioxidant enzyme such as SOD3 and CAT via up-regulating Nrf2 in human cancer cell MCF7, HeLa and SK-OV-3, concomitant with improved oxidative stress condition." (PMID 33558631, 2021).